C4A (complement C4A (Chido/Rodgers blood group))
Diseases named in the same sentence as C4A in open-access papers (continued):
Sharing a sentence is not in itself a finding about the gene and the disease.
infection (132 papers, 2008 to 2026). The state of being infected such as from the introduction of a foreign agent such as serum, vaccine, antigenic substance or organism. "It was also reported that the deficiency of either C4A or C4B has been associated with the increased susceptibility of infections." (PMID 34335607, 2021). "However, two of the studies revealed an association between slight infections prior to death and partial deletions of either the C4A or the C4B gene, which may indicate that this combination represents increased risk of sudden infant death." (PMID 25750641, 2015). "In blood neutrophils, in the steady state (e.g. Myc, H2-DMb2, H2-M3, H2-Q7...) but also during infection e.g. Cxcl10, H2-D1, C4a, Psme1, Stat1, Psme2, more genes were upregulated in neutrophils from female mice." (PMID 38179044, 2023). "The complement anaphylatoxins, C3a and C5a, and to a lesser extent C4a, are important modulators of the immune response to infection." (PMID 29581196, 2018). "We assessed changes in the concentration of complement fragments C3a, C4a, and C5a in mouse brain homogenates at pre-clinical and clinical times during 22L infection." (PMID 30596651, 2018). "Despite low titers of C4A and C4B during acute single strain infection, viral titers in the salivary gland of C4A and C4B singly infected mice at day 18 p.i. were not significantly different to those detected in C4C or C4D infected mice." (PMID 23300458, 2013). "At the sites where complement is activated during primary infection, there could be additional increases in the anaphylatoxins C3a, C4a and C5a, as has been reported." (PMID 35860286, 2022). "Interestingly, BALB/c mice experience significantly less expression of C4A at each infection time point compared to C57BL/6 mice which is an indication that there is decreased vascular permeability in these mice compared to B6." (PMID 33816350, 2021). "However, during multi-strain infection, both C4A and C4B were excluded from the salivary glands, while C4C and C4D replicated normally at this site." (PMID 23300458, 2013). "The C4a and C5 viruses isolated in Vietnam and Taiwan have similar antigenic profiles and could be neutralized by the post-infection children sera." (PMID 23922846, 2013). "The activity of the LP was evaluated by measuring the levels of oligomerized MBL, and a significant increase of MBL oligomerization was found in the DHF patients as compared to the DF patients during the acute phase of infection, which might have contributed to the elevated C4a level." (PMID 19707565, 2009). "In the present study, we observed an increase in the gene expression for complement including C6, C4A, CR2, C3 at 8wks post infection." (PMID 27467147, 2016). "Both C4A and C4C were detectable in the salivary glands of TC1 mice during single strain infection by plaque assay and by qPCR." (PMID 23300458, 2013). "Failure to detect C4A and C4B at this site was not simply due to mixed infection per se, as both these strains were able to disseminate to, and replicate within, the salivary gland when administered together." (PMID 23300458, 2013). "There were no statistical significance of the plasma concentrations of C1q, FB, MBL, C3, C3a, C4, C4a and sC5b-9 between the HBV-ACLF patients with infection and the HBV-ACLF patients without infection." (PMID 32293297, 2020).
tumor (120 papers, 1991 to 2026). "It has also been suggested that C4A promotes tumor growth through its interaction with tumor-associated macrophages." (PMID 40283026, 2025). "C4A may promote tumor growth by interacting with tumor-associated macrophages, potentially enhancing immune evasion and inflammation." (PMID 40283026, 2025). "Some members of the complement system can be modulated by the antifibrinolytic protein, activated thrombin-activatable fibrinolysis inhibitor (TAFIa), by inactivating the anaphylatoxins C3a, C4a and C5a and dysregulation of those genes has been implicated in tumor growth." (PMID 21718500, 2011). "Because only biomarkers that directly contribute to tumor growth may be targeted for therapy, the possibility of exploiting C4a as therapeutic target in HCC deserves further investigation in order to determine its role in tumor development." (PMID 25789864, 2015). "Furthermore, the serum concentrations of C4a were two-fold increased in patients with multinodular HCC when compared with patients with uninodular disease, and thus suggesting that more advanced HCC with increased tumor burden triggers the production of C4a." (PMID 25789864, 2015). "In addition to an altered metabolic phenotype, inflammation has been reported to play a significant role in the progression and treatment response of OAC tumours, whereby elevated levels of pro-inflammatory mediators such as LIF, C3a, C4a and IL-1β have been associated with poor treatment response." (PMID 32694701, 2020). "Therefore, upregulated plasma levels of C4a in HCV-infected patients with HCC may be associated with the immune response to HCV infection, alcohol consumption, and/or tumor antigens." (PMID 25789864, 2015). "Beyond their known functions, our study suggests that in BLCA, C4A, and CFI may also drive cancer progression by modulating immune-related checkpoints, offering additional insight into their role in tumor immunology." (PMID 40283026, 2025). "Furthermore, complement C3, C3a, C4, C4a, and C7 have been identified as biomarkers in HCC diagnosis while C7 and CFH are recognized for their critical roles in mediating stemness of tumor-initiating cells." (PMID 33718121, 2020).
cancer (69 papers, 1992 to 2026). A tumor composed of atypical neoplastic, often pleomorphic cells that invade other tissues. "Among them, TIMP1, LGALS3BP, A2M, AHSG, FN1, HRG, and ITIH4 have been associated with cancer, while CF I, C2, and C4A, have been related to complement activity." (PMID 37685286, 2023). "Several studies have surveyed that abnormal C4A expression is associated with some cancers." (PMID 34803909, 2021). "Mechanistically, we demonstrate that miR-29a and C4A act synergistically through SPARC down-modulation promoting cancer cell colonization." (PMID 42129855, 2026). "A meta-analysis of 50 complement-related genes across 30 cancers reported high expression of classical pathway components, such as C4A and C2, including in BLCA, consistent with our results." (PMID 40283026, 2025). "They recognized a significant expression of C3 and classical pathway components (C1QA, C1QB, C1QC, C1R, C1S, C4A, and C2) in all cancer types." (PMID 38003705, 2023). "Briefly, the high expression of seven blood group antigen genes, i.e., FUT7, AQP1, P1, C4A, AQP3, KEL, and DARC, was significantly associated with good prognosis in six types of cancers, i.e., KIRC, HNSC, LUAD, CESC, SARC, MESO." (PMID 35955933, 2022). "We compared serum levels of complement components (C3, C4, C1q), activation products (C3a, C4a, C5a, Ba, Bb, sC5b-9), and regulators (Factor I, Factor H) between patients who developed irMyositis or irNeuropathy, ICI-treated cancer patients without irAEs, and healthy controls." (PMID 40506552, 2025).
renal disease (39 papers, 2006 to 2025). "Proteins CFB, С3, C4A, and C4B are associated with the development of kidney diseases." (PMID 39896931, 2024). "However, the effects of C4a and C4b on other types of kidney disease and kidney function have not been verified." (PMID 38898508, 2024).
bacterial infection (10 papers, 2006 to 2024). "The role of the C4 isoforms (C4A and C4B) in Nm infection is conflicting with reports that C4 deficiency alone is not significant enough to predispose individuals to bacterial infection." (PMID 32067109, 2020).
psychiatric disorder (5 papers, 2012 to 2023). A disorder characterized by behavioral and/or psychological abnormalities, often accompanied by physical symptoms. "Among genes mapped to loci shared between AN and psychiatric disorders, several immune-related genes were implicated, including the C4A, C4B, NCAM1, HLA-B, HLA-C, and HLA-E genes." (PMID 37658054, 2023).
degenerative diseases (2 papers, 2012 to 2022). "These markers represent various physiological processes such as protein degradation (ubiquitin), protease inhibition (Cystatin C and Alpha-1-antichymotrypsin), and inflammation (C3a and C4a) that are known to be represented in neurodegenerative diseases." (PMID 22701795, 2012).
mitochondrial disease (1 paper, 2025). "A combined urinary biomarker panel—including stress markers (GDF15, CYCS, and PRDX2), immune effectors (MPO and C4A), ECM proteins (COL1A1 and CCN2), and selected amino acids—could support diagnosis, patient stratification, and longitudinal monitoring in mitochondrial disease." (PMID 41373442, 2025).
C4A also shares sentences with these, for which no sentence is quoted: nephritis (39 papers); viral infection (38); Thrombocytopenia (36); Hypertension (30); angioedema (29); cryoglobulinemia (26); vasculitis (23); Arthritis (21); lymphopenia (19); hereditary angioedema (18); anemia (17); glomerulonephritis (14); complement deficiency (13); glomerulosclerosis (11); metabolic syndrome (11); purpura (10); atherosclerosis (9); Hypoalbuminemia (8); Lymphadenopathy (8); monoclonal gammopathy (8); myocardial infarction (8); acute kidney injury (7); alopecia (7); acquired angioedema (6); cardiovascular diseases (6); connective tissue disease (6); glomerular diseases (6); Insulin resistance (6); interstitial lung disease (6); Obesity (6).
A further 350 diseases each share a sentence with C4A in 6 papers or fewer.